MIR199B (microRNA 199b)
Synonyms: hsa-mir-199b; MIRN199B; mir-199b
Gene: MicroRNA gene on chromosome 9 (128,244,721 to 128,244,830, reverse strand). Ensembl gene ENSG00000207581.
Gene Ontology:
Biological process: miRNA-mediated post-transcriptional gene silencing
Cellular component: RISC complex
Homologues: Orthologues: chimpanzee ptr-mir-199b (100% identical), guinea pig MIR199B (100% identical), macaque MIR199B (100% identical), mouse Mir199b (98% identical), pig MIR199B (96% identical), zebrafish mir199-1a (59% identical), zebrafish MIR199B (53% identical). Paralogues in human: MIR199A2 (64% identical), MIR199A1 (54% identical).
Diseases named in the same sentence as MIR199B in open-access papers:
MIR199B is named in the same sentence as 1 disease in open-access papers, as found by Europe PMC text mining. Sharing a sentence is not in itself a finding about the gene and the disease.
MIR199B shares sentences with these, for which no sentence is quoted: diabetes (1 paper).